IRS1 (insulin receptor substrate 1)
Diseases named in the same sentence as IRS1 in open-access papers (continued):
Sharing a sentence is not in itself a finding about the gene and the disease.
tumor (243 papers, 2004 to 2025). "The results indicated that high-level IGF1 and IRS1 expression in GC is significantly associated with a more aggressive tumor phenotype." (PMID 36774408, 2023). "IRS1 was overexpressed in tumor cells and this was associated with a shorter patient survival time and an increase in 8-oxodG." (PMID 36768755, 2023). "During osteosarcomagenesis and progression, IRS1 executes important regulatory functions and participates in the control of various tumor-associated malignant activities." (PMID 35030964, 2022). "In support of our data, it has been shown that overexpression of IRS1 causes cell transformation and constitutively active IRS1 promotes tumor growth in various human cancers." (PMID 33976188, 2021). "When dichotomized by low and high cytoplasmic IRS-1 expression, low expression was significantly associated with less nodal involvement (p = 0.009) and tumor grade (p = 0.041) at diagnosis." (PMID 31393907, 2019). "In A549 lung adenocarcinoma, neutrophil elastase (NE) degrades IRS-1 in cancer cells, thereby causing tumor cell proliferation." (PMID 31474975, 2019). "Results obtained from these studies clearly indicate that downregulation of miR-1225-5p in GC is associated with upregulation of IRS1 and activation of β-catenin signaling pathway, thus contributing to the tumor growth and metastasis." (PMID 26684358, 2016). "The association of IRS-1 expression with BRCA1 provides additional support for the involvement of this IRS family member in tumor initiation." (PMID 19534786, 2009). "Both of these signaling pathways have been implicated in promoting tumor cell proliferation, invasion and survival, but they cannot explain the differential abilities of IRS-1 and IRS-2 to regulate these functions." (PMID 19534786, 2009). "On the other hand, restoration of miR-145 expression has been associated with inhibition of tumor cells growth via downregulation of IRS-1." (PMID 19912656, 2009). "Furthermore, our gain and loss of functional experiments showed that a PTEN/IRS1 axis is essential for the NEDD4-targeted inhibitory effect on tumor growth in IGF1 signaling-driven GC." (PMID 36774408, 2023). "Similarly, IRS1 expression is associated with tumor differentiation grade and tumor invasion in patients with GC." (PMID 36774408, 2023). "Additional studies indicated that knockdown of IRS-1 expression prevented the effects of Smad3-deficiency on cell proliferation and apoptosis, indicating that TGFβ/Smad3 mediates tumor suppressor function through the inhibition of IRS-1 expression and activation." (PMID 28414818, 2017). "Moreover, one study showed that partial or absolute IRS-1 deficiency reduces the tumor load in APCmin/+ mice." (PMID 23877285, 2013). "Loss of feedback inhibition in tumours treated with mTOR inhibitors (via increased expression of IRS-1) results in induction of AKT signalling, and may be responsible for the disappointing efficacy of mTOR antagonists in the clinic." (PMID 21909357, 2011). "These in vitro findings support the hypothesis that Irs-2 compensates for the loss of Irs-1, and in doing so, enhances the activation of signaling pathways that promote tumor metastasis." (PMID 19534786, 2009). "For instance, TANs-secreted NE has been shown to promote tumor growth in a mouse model of lung ADC by degrading insulin receptor substrate-1 (IRS-1)." (PMID 41023740, 2025). "Enhanced IRS-1 expression is essential in the activation of AKT which further promotes tumor spheroid growth." (PMID 41271627, 2025). "They found that NE can directly enter the intracellular compartments of tumor cells through endocytosis, where IRS-1 was degraded, ultimately leading to tumor cell proliferation." (PMID 38750338, 2024). "Cul7 also exerts a tumor suppressor effect, as evidenced in part by the degradation of IRS-1 via the mTOR pathway." (PMID 39852134, 2024).
tumor (continued). "In MCF-7 tumor cell lines, estradiol facilitates insulin signaling through an increased expression of insulin receptor substrate-1 (IRS-1)." (PMID 39329990, 2024). "The Western blot results revealed that the changes in the expression of cell cycle‐related proteins, apoptosis‐related proteins and tumour metastasis‐related proteins were abolished after IRS1 was overexpressed in PYCR1‐knockout or PYCR1‐inhibited LC cells." (PMID 39422696, 2024). "The results of their study showed that miR-126 can function as a tumor suppressor via the regulation of insulin receptor substrate 1 (IRS1) and GOLPH3." (PMID 37185715, 2023). "ELANE also can degrade insulin receptor substrate 1 and activate the phosphatidylinositol 3 kinase-protein kinase B signaling pathway, thereby promoting the proliferation of tumor cells." (PMID 37596368, 2023). "We demonstrate that increased expression of RUNX3 and SMAD4 in tumor epithelial and stromal compartments and IRS-1 in stroma are independent predictors of a favorable prognosis in this patient group." (PMID 36900240, 2023). "To test the effect of IRS-1 inhibition on tumor progression in vivo, we engrafted luciferase-tagged 92.1 cells (a UM cell line) on the chicken CAM to generate UM xenografts." (PMID 36551732, 2022). "The expressions of INSR, IRS-1, and PD-L1 proteins in tumor tissues and adjacent tissues of NSCLC were detected by immunohistochemical staining." (PMID 36245982, 2022). "The NT compounds are highly effective in anti-cancer activity because they inhibit both the tumor growth promoted by IRS-1 and IRS-2-mediated metastasis." (PMID 36551732, 2022). "IRS-1/2 are intermediates of multiple receptors that control tumor progression and thus can play an important role in the response of tumor cells to different microenvironmental signals." (PMID 36551732, 2022). "It is reported that the expression of IRS-1 is increased in hepatocellular, pancreatic, and prostate cancer, while its expression is negatively correlated with tumor progression in breast cancer." (PMID 34443299, 2021). "Researchers have found that IGF-1R/IRS1 signaling pathway is also related to the adhesion process among malignant tumor cells, and plays an important role in the phenotype maintenance of cancer cells and the process of anti-tumor treatment resistance." (PMID 34837929, 2021). "IRS-1 is responsible for tumor proliferation, whereas IRS-2 promotes cancer cell motility and invasion." (PMID 33991522, 2021). "Here, we demonstrate that IGFBP‐3 inhibits cell growth by stimulating the TβR‐V‐mediated tumor suppressor signaling pathway (TβR‐V/IRS‐1/2/PP2A/p130, p107)." (PMID 34485840, 2021). "We subsequently examined the effect of exosomal miR-145 from STIM1-KO-MDA-MB-231 cells on the IRS1 pathway, which is the key pathway regulating tumor angiogenesis." (PMID 33414420, 2021). "As for LSCC, downregulated miR-144-3p has been reported as performing a tumor-suppressive role by targeting insulin receptor substrate 1 (IRS1) and E26 transformation specific-1 (ETS1)." (PMID 34326893, 2021). "Pool2 cells stably transfected with control shRNA or IRS1-specific shRNA were subcutaneously inoculated into nude mice to establish tumor xenografts." (PMID 33976188, 2021). "Since IRS-1 is a crucial intermediate for multiple receptors and signaling pathways that can influence tumor progression, it is a pivotal target for therapeutic intervention." (PMID 33991522, 2021). "The C134 virus is a replication-competent virus that can infect and kill tumor cells and induce an anti-tumor immune response facilitated by the IRS1 transgene which helps in evading PKR-mediated protein shutoff." (PMID 34372501, 2021). "miR-145 has been repeatedly reported to be a tumor suppressor, and to target gene IRS1 and therefore inhibit its protein expression." (PMID 33414420, 2021). "This is associated with the increased expression of insulin receptor substrate 1 (IRS1) in tumor cells." (PMID 33046994, 2020).
tumor (continued). "In LSCC, the lncRNA X-Inactive Specific Transcript (XIST) promotes the tumor progression by sequestering miR‐144 to regulate IRS1 expression." (PMID 33046994, 2020). "While CUL7 also exerts a tumor-suppressive effect, as partially proven by the degradation of IRS-1, which is negatively mediated via the mTOR pathway." (PMID 33130829, 2020). "miR-126 negatively regulates insulin receptor substrate 1 (IRS-1), Kristen rat sarcoma viral oncogene (KRAS), and GATA binding protein 4 (GATA4) and its loss is implicated in tumor progression." (PMID 32906592, 2020). "IR substrates (IRS)-1 and -2 also contribute to disease development: IRS-1 overexpression is associated with metastasis, whereas IRS-2 is related to early-stage tumor formation." (PMID 33396628, 2020). "The suppression of IRS1 and the activation of IL-6 are both reported to induce or promote tumor metastasis." (PMID 30741955, 2019). "We verified that the tumour development, as a time-course analysis, the phospho IRS1/total-IRS1 ratio was decreased in W group at 7th and 14th day after tumour implant in comparison to control group." (PMID 30975087, 2019). "Ectopic miR-126 inhibited IRS1, thus resulting in metabolic changes and consequent tumor suppression." (PMID 31850200, 2019). "We sequenced the coding regionssurrounding YXXM motifs of IRS1 using tumor samples of 42 NSCLC patients and 40matching controls and found heterozygote p.S668T mutation in nine of 42 samplesand four of nine also had the p.D674H mutation." (PMID 30807634, 2019). "A reduction of IRS-1 expression in more advanced tumors has been observed in other cancer types and supports a suppressive role for IRS-1 signaling in tumor progression." (PMID 31393907, 2019). "Overall, the transcript levels of p63 and IRS1 are significantly higher in tumour specimens than in normal samples." (PMID 30594912, 2018). "In a series of experiments they demonstrated that removal of IRS1 in the tumor cells line investigated lead to unrestricted growth factor independent mitosis, whereas the overexpression of IRS1 or inhibition of NE proteolytic activity reduced proliferation." (PMID 30298053, 2018). "High expression of IGF-1R due to phosphorylated activity of IRS-1 can enhanced activity of ER-α which leads the tumor towards metastasis." (PMID 29787591, 2018). "Exosomal MiR-126 derived from HUVECs was found to interact with MNSC cells, leading to increased MiR-126 levels, whereby inducing anti-tumour responses such as inhibition of cell proliferation and target gene modulation including IRS1 and VEGF." (PMID 30223817, 2018). "Consistent with our previous studies, these results suggested that miR-30e inhibited tumor growth through targeting IRS1 and other downstream signaling molecules in vivo." (PMID 29162879, 2017). "Loss or attenuation of TGFβ signaling leads to elevated expression and activation of IRS-1, resulting in enhanced cell proliferation, decreased apoptosis and increased tumor growth in vitro and in vivo." (PMID 28414818, 2017). "Comparative analysis between the tumors and matched non-tumor tissues in each individual mouse revealed that Irs1 mRNA expression was indeed significantly upregulated in the tumors." (PMID 28710407, 2017). "In this context, our data closely mirror the observation in tumor cells, in that exogenous NE added to BeWo degraded IRS1." (PMID 28659928, 2017). "The results showed that the average expression levels of IRS1 were significantly higher in tumor tissues than those in the adjacent normal tissues." (PMID 29162879, 2017). "In agreement with in vitro studies, the levels of IRS1 from the tumor tissues of miR-30e-expressing group were lower than that of miR-NC group by immunoblotting assay." (PMID 29162879, 2017). "On the basis of these findings, we propose that the increased level of β-catenin in HCC, which is observed in approximately 50–70% of HCC29, provides a growth advantage to tumor cells by promoting their proliferation via upregulation of Irs1." (PMID 28710407, 2017).
tumor (continued). "PTPN13 as tumour suppressor gene induced cell apoptosis via inhibition of the IRS‐1/PI3K/Akt signalling pathway." (PMID 28653805, 2017). "While a tendency towards increased tumor Irs2 mRNA expression was also noted, the increase in the tumor: non-tumor tissue expression ratio was significantly higher for Irs1 mRNA than for Irs2 mRNA." (PMID 28710407, 2017). "In the first of these pivotal reports, it was shown that exogenously liberated NE uncoupled tumor cell signaling via the degradation of IRS1, leading to deregulated proliferation." (PMID 28659928, 2017). "MiR-30e also inhibited tumor growth and suppressed expression of IRS1, AKT, ERK1/2 and HIF-1α in mouse xenograft tumors." (PMID 29162879, 2017). "IRS1 has been shown to promote Wnt-β-catenin signaling which induce transcription of downstream genes related to tumor growth and metastasis." (PMID 26684358, 2016). "To examine the ability of Pim inhibitors to function in vivo to inhibit tumor growth and regulate IRS1 phosphorylation, we injected NSG mice with H-SB2, T-ALL cells expressing luciferase and administered AZD1208 by oral gavage." (PMID 26956053, 2016). "IRS1 serves as a signal adaptor protein in oncogenic transformation by coordinating and amplifying numerous signals within the tumor cells." (PMID 26684358, 2016). "IRS1 has also been shown to interact with β-catenin whose activation induces the expression of several genes involved in tumor growth and metastasis." (PMID 26684358, 2016). "Taken together, these results suggest that the tumor-suppressive effect of miR-1225-5p is mediated, at least in part, through inhibition of IRS1." (PMID 26684358, 2016). "In fact, miR-145 has been well documented as a tumor suppressor gene because it negatively regulates multiple oncogenes such as Myc, K-Ras, IRS-1, ERK5." (PMID 25928322, 2015). "In OS, altered IRS-1 expression inhibits osteoblastic differentiation and enhances tumor malignancy." (PMID 26029165, 2015). "Although IRS-1 is most often related to tumor growth and proliferation, IRS-2 is most frequently associated with tumor motility and invasion." (PMID 26029165, 2015). "Here, we demonstrated that this compound inhibits tumor growth, cell cycle, and the motility of OS cells via the downregulation of IRS-1/IRS-2 proteins and their downstream mediators." (PMID 26029165, 2015). "The maximal activity was reached already after 24 h of treatment, confirming that the inhibitory effects on tumor growth in OS were related to destruction of IRS-1." (PMID 26029165, 2015). "In this context, NE targeted critical components of intracellular signaling cascades, including IRS-1 and cyclin E, promoting tumor growth." (PMID 25551582, 2014). "Literatures also report that NE secreted from neutrophils is a prognostic marker, and can trigger tumor proliferation via degrading IRS-1 in tumor cells." (PMID 24457622, 2014). "Another important fact is that RAD001 is known to activate insulin receptor substrate 1 (IRS-1)-Akt signaling, which is suggested to potentially attenuate its effects on tumor cell proliferation and viability." (PMID 24416349, 2014). "The 5- to10-fold increase in ED50 relative to the EC50 obtained for 32D hIGF1R/IRS-1 cells in vitro is expected given tumor resistance to antibody penetration." (PMID 23383308, 2013). "Emerging studies showed that miR-145 is a putative tumor-suppressive gene that is down-regulated in several types of tumors and inhibits cell growth by targeting c-Myc and IRS-1." (PMID 23301032, 2013). "It is thought to have a tumor-suppressor role, partly by targeting the insulin receptor substrate 1 (ISR-1) and type I insulin-like growth factor receptor (IGF-IR)." (PMID 22529906, 2012). "This suggests that tumour cells can escape cell death through additional mechanisms other than the p70S6K/IRS-1/PI3K/Ras feedback loop." (PMID 22647622, 2012).
tumor (continued). "A general theme arises from these studies; IRS-1 and IRS-4 are most often associated with tumor growth and proliferation and IRS-2 is most often associated with tumor motility and invasion." (PMID 19534786, 2009). "Similar to IRS-1, IRS-2 has also been implicated in promoting tumor cell survival, which is likely to contribute to its role in tumor progression." (PMID 19534786, 2009). "IGF1R has both mitogenic and antiapoptotic roles in tumor development via signaling through the phosphatidylinositol-3-kinase and mitogen-activated protein kinase pathways, with its adaptor protein IRS1 critical in activating the downstream pathways." (PMID 19843326, 2009). "IRS-1 involvement in regulating tumor cell proliferation was foreshadowed by its role in somatic growth regulation." (PMID 19534786, 2009). "Additionally, LIN28B contributes to CRC tumor growth through the LIN28B/IRS1 axis, a target of miR-30a-5p, which promotes tumor proliferation." (PMID 40746360, 2025). "In addition, immunohistochemistry was performed on tumour tissues from previous animal experiments, confirming the downregulation of IRS1 after the knockdown/inhibition of PYCR1 in vivo." (PMID 39422696, 2024). "IRS-1, the critical molecule downstream of insulin and insulin-like growth factor 1 receptor, can be ubiquitinated by Cul7 E3 ligase, suggesting that this tumor-suppressing activity may be related to Cul7-mediated degradation of IRS-1." (PMID 39852134, 2024). "The study showed that miR-150-5p/3p could inhibit tumor migration and invasion both in vitro and in vivo by regulating insulin receptor substrate-1 and Insulin-Like Growth Factor 1 Receptor (IGF1R)." (PMID 39770446, 2024). "Indeed, miR-145 has been well established as a tumor suppressor gene due to its negative regulation of various oncogenes such as Myc, K-Ras, IRS-1, and ERK5." (PMID 37513415, 2023). "Moreover, ADIRD-AS1 impedes tumor growth and is a competitive endogenous RNA for miR-761 as it is removed from IRS1, leading to increased IRS1 overexpression." (PMID 36831374, 2023). "Moreover, insulin receptor substrate 1 (IRS1) activation of PI3K signaling also mediates tumor propagation as neutrophil elastase metastasizes to cancer cells." (PMID 37404749, 2023). "Therefore, in these experiments, we validated in vivo the inhibitory effect of IRS-1 blocking on tumor cell growth." (PMID 36551732, 2022). "Besides, MiR-7 can target p21-activated kinase 1, epidermal growth factor receptor, and insulin receptor substrate 1 to influence biological processes like proliferation, migration, apoptosis, and cell cycle of tumor cells in CRC by targeting." (PMID 36199554, 2022). "In tumor cells, neutrophil elastase (NE) can inhibit insulin receptor substrate-1 (IRS-1)." (PMID 36419156, 2022). "IRS1/2 overexpression stimulated metastasis and tumor formation." (PMID 36140796, 2022). "In addition, NE was shown to stimulate tumor cell proliferation by degrading the insulin receptor substrate-1 (IRS-1), resulting in an increased interaction between phosphatidylinositol kinase-3 (PI3K) and platelet-derived growth factor receptor (PDGFR)." (PMID 36613577, 2022). "Our results indicated that the activated PKA in untreated tumor-bearing mice could activate IRS-1, as evidenced by increased mRNA expression levels of IRS-1." (PMID 35798765, 2022). "IRS-1 may be involved in the regulation of PD-L1 expression and mediate the occurrence of tumor immune escape, which is expected to become a new target for NSCLC immunotherapy and provide new clinical evidence for immunosuppressive therapy." (PMID 36245982, 2022). "Therefore, we have reason to believe that INSR and IRS-1 are involved in the process of glycolysis metabolism and play an important role in maintaining the survival and proliferation of tumor cells." (PMID 36245982, 2022).